ARHGAP19-SLIT1 (ARHGAP19-SLIT1 readthrough (NMD candidate))
Gene: Protein-coding gene on chromosome 10 (97,153,045 to 97,292,637, reverse strand). Ensembl gene ENSG00000269891.
Genetic constraint (gnomAD): Missense variants: 522 observed, 585.03 expected, observed/expected ratio (o/e) 0.89, 90% interval 0.83 to 0.96. Synonymous variants: 199 observed, 214.22 expected, observed/expected ratio (o/e) 0.93, 90% interval 0.83 to 1.04.